KCNIP4 (potassium voltage-gated channel interacting protein 4)
Description:
Regulatory subunit of Kv4/D (Shal)-type voltage-gated rapidly inactivating A-type potassium channels. Modulates KCND2 channel density, inactivation kinetics and rate of recovery from inactivation in a calcium-dependent and isoform-specific manner. Modulates KCND3/Kv4.3 currents. Isoform 4 does not increase KCND2 expression at the cell membrane. Isoform 4 retains KCND3 in the endoplasmic reticulum and negatively regulates its expression at the cell membrane.
Synonyms: KChIP4; CALP; MGC44947
Tractability: Antibody: UniProt places it where antibodies can reach, with high confidence; its Gene Ontology location is reachable by antibodies, with high confidence. PROTAC: ubiquitination databases record sites on it; its protein half-life has been measured.
Safety:
Unwanted effects reported when the protein is acted on. In parentheses: how it was acted on, where the effect was seen, and who reports it.
ACE inhibitor induced cough (source: ClinPGx)
Gene: Protein-coding gene on chromosome 4 (20,728,606 to 21,948,772, reverse strand). Ensembl gene ENSG00000185774.
Subcellular location: Cell membrane; Cytoplasm; Peroxisome; Endoplasmic reticulum (Isoform 4)
Subcellular location (Human Protein Atlas): Vesicles
Pathways (Reactome):
Muscle contraction: Phase 1 - inactivation of fast Na+ channels
Gene Ontology:
Molecular function: calcium ion binding; protein binding; potassium channel regulator activity
Biological process: protein localization to plasma membrane; regulation of potassium ion transmembrane transport; regulation of signal transduction
Cellular component: cytoplasm; endoplasmic reticulum; peroxisome; plasma membrane; cytosol; voltage-gated potassium channel complex
Genetic constraint (gnomAD): Loss-of-function variants: 6 observed, 13.86 expected, observed/expected ratio (o/e) 0.43, 90% interval 0.24 to 0.85. The upper end of that interval is the gene's LOEUF score, 0.85, which puts it in group 3 of 6, group 1 being the genes least tolerant of losing a copy. Missense variants: 138 observed, 172.11 expected, observed/expected ratio (o/e) 0.8, 90% interval 0.7 to 0.92. Synonymous variants: 66 observed, 58.42 expected, observed/expected ratio (o/e) 1.13, 90% interval 0.93 to 1.39.
Homologues: Orthologues: chimpanzee KCNIP4 (100% identical), macaque KCNIP4 (100% identical), mouse Kcnip4 (99% identical), pig KCNIP4 (99% identical), dog KCNIP4 (92% identical), rabbit KCNIP4 (92% identical), rat Kcnip4 (92% identical), tropical clawed frog kcnip4 (80% identical), guinea pig KCNIP4 (56% identical), zebrafish kcnip4b (54% identical), Drosophila melanogaster CG5890 (39% identical), Caenorhabditis elegans ncs-7 (30% identical), and 2 more. Paralogues in human: KCNIP2 (67% identical), KCNIP3 (64% identical), KCNIP1 (61% identical), NCS1 (34% identical), VSNL1 (33% identical), HPCA (31% identical), HPCAL4 (30% identical), NCALD (30% identical), HPCAL1 (30% identical), RCVRN (24% identical), GUCA1B (22% identical), CLXN (21% identical), and 2 more.
Diseases named in the same sentence as KCNIP4 in open-access papers:
KCNIP4 is named in the same sentence as 33 diseases in open-access papers, as found by Europe PMC text mining. Sharing a sentence is not in itself a finding about the gene and the disease. The quoted sentences say what the papers report.
schizophrenia (4 papers, 2017 to 2025). A major psychotic disorder characterized by abnormalities in the perception or expression of reality. "In this study, we found a strong association between the KCNIP4 gene and adverse reactions during aripiprazole treatment in schizophrenia patients, while KCNA1/Kv1.1 also showed a significant association (rs57468930, P = 1.56 × 10−6)." (PMID 37491364, 2023). "The KCNIP4 was significantly associated with ADHD, autism, schizophrenia, bipolar and major depressive disorder, and this also suggested that K+ channel-related calcium regulator protein may be a common genetic basis in various mental disorders." (PMID 37491364, 2023). "Multiple differentially expressed genes (KCNIP4, GRM3, PRKG1, NPY for inh-C, and TRPC3 for inh-CCK) were related to glutamate reception and calcium channel activity, indicating these processes are altered within inhibitory midbrain neurons in schizophrenia." (PMID 39397771, 2025). "The network analysis of the 7 annotated genes revealed 5 networks, each with PARK2, N4BP2, KCNIP4, ADGRL2, or NCOA7 as its focus gene, which may have joint influence on the initiation of schizophrenia." (PMID 28744025, 2017).
Alzheimer disease (2 papers, 2013 to 2024). A progressive, neurodegenerative disease characterized by loss of function and death of nerve cells in several areas of the brain leading to loss of cognitive function such as memory and language. "The protein encoded by KCNIP4 was first identified in a study searching for proteins that interacted with presenilins, which are linked to early-onset Alzheimer’s disease." (PMID 23457522, 2013).
asthma (2 papers, 2013 to 2020). "Based on the mouse and human association results, the Kv channel interacting protein 4 (KCNIP4) emerged as the gene most likely to be related to asthma and AHR." (PMID 23457522, 2013). "First, a small GWAS of toluene diisocyanate-induced asthma in Koreans (84 cases and 263 controls) found that KCNIP4 SNP rs4697192 had a P-value of 6.11e-05 for association under a recessive model." (PMID 23457522, 2013). "Functional studies are required to validate the potential involvement of KCNIP4 in modulating asthma susceptibility and/or AHR." (PMID 23457522, 2013). "Following validation attempts in three human asthma GWAS (i.e., Sepracor/LOCCS/LODO/Illumina, GABRIEL, DAG) and two human AHR GWAS (i.e., SHARP, DAG), the Kv channel interacting protein 4 (KCNIP4) gene was identified as nominally associated with both asthma and AHR at a gene- and SNP-level." (PMID 23457522, 2013). "In addition to the nominal associations we observed, other studies have observed KCNIP4 SNP associations with asthma-related phenotypes." (PMID 23457522, 2013). "Each asthma GWAS had a different top hit in each region, and only KCNIP4 showed evidence of SNP-level replication at a nominally significant threshold." (PMID 23457522, 2013). "While there was some evidence of gene- or regional-level replication for both sites among the GABRIEL and Sepracor/LOCCS/LODO/Illumina asthma GWAS studies, only the KCNIP4 gene had evidence of replication at individual SNPs." (PMID 23457522, 2013). "After attempting to confirm our results in three additional asthma GWAS and two AHR GWAS, we found that the Kv channel interacting protein 4 (KCNIP4) is likely to be related to asthma and AHR." (PMID 23457522, 2013). "Of the top two regions, KCNIP4 and PDZD2/GOLPH3/MTMR12/ZFR, only KCNIP4 had gene-level replication in the SHARP AHR GWAS at a nominally significant level in the same regions as the asthma GWAS studies." (PMID 23457522, 2013). "Thus, one possible mechanism by which KCNIP4 may influence asthma and AHR is via modulation of intracellular calcium." (PMID 23457522, 2013). "Taken together, the KCNIP4 association results from the current study and three previous ones suggest that if the nominally significant associations found represent a true relationship between this gene and asthma, then there is not a clear single functional variant underlying this relationship." (PMID 23457522, 2013). "In summary, integration of genome-wide association results for a mouse strain survey of baseline AHR with human asthma and AHR GWAS results suggests that KCNIP4 is a gene related to both asthma and AHR." (PMID 23457522, 2013). "We found that there was additional gene-level and SNP-level replication for KCNIP4 with asthma in DAG, and gene-level replication for KCNIP4 with AHR in DAG." (PMID 23457522, 2013). "Additionally, only KCNIP4 SNPs were nominally associated with AHR among asthmatics in the SHARP AHR GWAS, indicating that this gene may be related to both baseline AHR (i.e. AHR in the absence of asthma) and asthma." (PMID 23457522, 2013).
cerebellar ataxia (2 papers, 2020). A neurological syndrome characterized by clumsy and uncoordinated movement of the limbs, trunk, and cranial muscles. "The present study used a much larger number of in-house and consortium control sequences to filter variants to a level manageable for follow-up, allowing the discovery of a likely-pathogenic variant in KCNIP4, a novel gene for cerebellar ataxia." (PMID 31999692, 2020). "A mutation within KCNIP4, a novel gene for cerebellar ataxia, was identified." (PMID 31999692, 2020). "In addition to demonstrating that a variant within KCNIP4 causes cerebellar ataxia in the Norwegian Buhund dog breed, we have characterised the gene’s expression in the canine cerebellum." (PMID 31999692, 2020). "RT-PCR of RNA extracted from cerebellum tissue samples from two ataxia-affected Buhunds and five unaffected dogs of other breeds confirmed that at least five transcripts for KCNIP4, with alternative first exons, are expressed in the canine cerebellum." (PMID 31999692, 2020). "Mutations in KCNIP4 have not been associated with cerebellar ataxia previously in any species to the authors’ knowledge." (PMID 31999692, 2020). "The mutation is in a gene, KCNIP4, not previously implicated in this disease in any species, and these findings could therefore inform research into inherited ataxia of unknown aetiology in humans." (PMID 31999692, 2020).
Cough (2 papers, 2020 to 2023). A sudden, audible expulsion of air from the lungs through a partially closed glottis, preceded by inhalation. "A GWAS on ACEi-induced cough detected an association with the calcium-activated potassium channel gene KCNMB2, while another GWAS found an association with the calcium-binding potassium channel-interacting protein gene KCNIP4." (PMID 32080354, 2020).
personality disorder (2 papers, 2020 to 2022). A diverse category of psychiatric disorders characterized by behavior that deviates markedly from the expectations of the individual's culture; this pattern of deviation is pervasive and inflexible and is stable over time. "The GTP-binding RAS-like 2 gene (DIRAS2), which regulates neurogenesis, as well as protein phosphatase 2, regulatory subunit B, gamma (PPP2R2C) gene located in the 4P16 region, channel-interacting protein 4 (KCNIP4) and SPOCK gene, is also associated with adult ADHD and personality disorders." (PMID 36317794, 2022). "In a study assessing personality disorders, adult ADHD and family-based childhood ADHD, Kv channel-interacting protein 4 (KCNIP4) gene, suggested to be part of a negative feedback loop in the Wnt/β-catenin pathway, was found to associate with ADHD58." (PMID 32948744, 2020).
Arthritis (1 paper, 2025). Inflammation of a joint. "RO/E indices further indicated a positive association of Mac_Adam8 (1.59) and Mac_mt-Co1 (1.64) with arthritis and spondylitis, whereas Mac_Kcnip4 (0.38), Mac_Retnla (0.08), Mac_Spic (0.64), and Mac_Vsig4 (0.52) were negatively correlated (p < 0.05)." (PMID 41459160, 2025).
Cognitive impairment (1 paper, 2024). Abnormal cognition is characterized by deficits in thinking, reasoning, or remembering. "Further, the expression of transcription factor Esrra was decreased, which regulated the gene Kcnip4 associated with cognitive impairment in the ExN1 and ExN3 subpopulations." (PMID 39635132, 2024).
ischemic heart disease (1 paper, 2016). "KCNIP4, a member of the voltage-gated potassium (Kv) channel-interacting protein family, has been reported to be associated with ischemic heart disease." (PMID 26930585, 2016).
liver disease (1 paper, 2025). "Interestingly, many of the genes linked to the differentially methylated CpGs have been associated with liver disease progression (eg, DCP2, TRPV3, ARRB1, KCNIP4, MIR10A) and cancer formation or progression (eg, MTHFR, GRIK2, GSN, HOX3, KCNMA1)." (PMID 40275933, 2025).
mental disorder (1 paper, 2023). A disease that has its basis in the disruption of mental process. "In conclusion, the KCNIP4 gene is deeply involved in normal brain function activities, and its gene polymorphism is generally associated with mental disorders." (PMID 37491364, 2023).
renal cell carcinoma (1 paper, 2021). "Previously, the disruption of KCNIP4 has been observed in patients with renal-cell carcinoma." (PMID 34593906, 2021).
tumor (3 papers, 2018 to 2023). "For the four newly discovered tumor suppressor genes, i.e., KCNIP4, CACNA1C, PACRG, and ST6GALNAC3, previous studies have proved their regulatory effect in tumors." (PMID 35321246, 2022). "Transcriptome and survival analyses revealed four potential tumor suppressor genes including KCNIP4, CACNA1C, PACRG, and ST6GALNAC3." (PMID 35321246, 2022).
nervous system diseases (1 paper, 2023). "The important functional genes found in this study, such as SLC22A8, ADCYAP1R, and KCNIP4, will be important candidates for further research on the molecular signaling pathways of mental and nervous system diseases." (PMID 37491364, 2023).
KCNIP4 also shares sentences with these, for which no sentence is quoted: cancer (3 papers); acute kidney injury (1); acute myelogenous leukemia (1); Ataxia (1); autism (1); cerebellar degeneration (1); cholestasis (1); heart failure (1); hyperadrenocorticism (1); inflammation (1); inflammatory bowel disease (1); leukemia (1); major depressive disorder (1); melanoma (1); neurodevelopmental disorder (1); osteosarcoma (1); partial epilepsy (1); Sepsis (1); spondylitis (1).